ARID1A (AT-rich interaction domain 1A)
Diseases named in the same sentence as ARID1A in open-access papers (continued):
Sharing a sentence is not in itself a finding about the gene and the disease.
cancer (continued). "Mutations in epigenetic modifier enzymes KMT2B, KMT2C, KMT2D, and ARID1A were more prevalent in MSI cancers, where the majority possessed KMT2B and KMT2D mutations and over one-third had KMT2C and ARID1A mutations (χ2 test p = 0.001)." (PMID 37998722, 2023). "ARID1A is a cBAF-specific subunit and the most frequently mutated SWI/SNF subunit across cancer types." (PMID 37093326, 2023). "In 2013, two independent studies described that approximately 20% of all human cancer types harbor mutations in the mammalian SWI/SNF complex and that the ARID1A gene has the highest mutational rate between 4.6% and 9%." (PMID 37627124, 2023). "In drug sensitivity analysis, we found that low expression of these four genes (TTN, ARID1A, KDM6A, and RB1) was positively associated with resistance to cancer therapeutics response portal (CTRP)." (PMID 37065485, 2023). "In this review, we explore the key metabolic mechanisms that underpin the immunomodulatory role of AT-rich interaction domain 1A (ARID1A), the most frequently mutated epigenetic regulator across human cancers." (PMID 36980292, 2023). "A study to evaluate the loss of function of ARID1A and ARID4B in both normal and cancer cells is necessary to verify specific effects on the TGF-β pathway, such as adding exogenous TGF-β in a rescue study." (PMID 38137006, 2023). "Additional clinical studies are still required to understand better the connection between YM155 and malignant tumors that diminish the ARID1A gene." (PMID 38008753, 2023). "Compared with the wild-type, the loss of ARID1A in MDA-MB-231 and BT-549 cell lines resulted in significant pseudopodia, which contributed to the migration of cancer cells." (PMID 37173914, 2023). "Being downregulated, the tumor suppressor gene ARID1A promotes cancer development through perturbations in the DNA-damage response and by activation of the PI3K/AKT/mTOR cell-cycle pathway." (PMID 37175555, 2023). "Therefore, a deeper understanding of the immunomodulatory effects of PI3K/AKT/mTOR inhibitors may pave the way for their efficient combination with other therapeutic agents, including immune checkpoint blockers, to enhance clinical outcomes for patients with ARID1A‐deficient cancers." (PMID 38041544, 2023). "To differentiate the context dependence on ARID1A in cancers carrying either wildtype or mutant ARID1A, we analyzed the cell type dependencies on ARID1A across 32 cancer types." (PMID 36980292, 2023). "Most ARID1A mutations in MSI GC involve short mononucleotide repeat insertions or deletions, which are uncommon in cases of microsatellite‐stable cancer." (PMID 38041544, 2023). "These agents have the potential to exploit synthetic lethal interactions to selectively target ARID1A‐mutant cancer cells." (PMID 38041544, 2023). "Certain studies have suggested that cancers (especially EC) with multiple ARID1A alterations have higher TMB and markedly high immune infiltration levels; this indicates the value of ARID1A alterations as a predictive biomarker for response to ICI treatment." (PMID 36793735, 2023).
cancer (continued). "ARID1A is generally considered a tumor suppressor gene that can inhibit the biological behavior of malignant tumors and regulate the cell cycle to promote apoptosis to exert anticancer effects." (PMID 38008753, 2023). "ARID1A can be a screening biomarker for individuals whose cancer is responsive to targeted therapy and immunotherapy." (PMID 38008753, 2023). "For instance, depletion of ARID1A leads to a reduction in the open histone mark (H3K27ac) at the gene enhancer regions, which in turn transcriptionally downregulates several cancer genes, such as PIK3IP1, SLC7A11, CDKN1A, TGF-β receptor, and SMAD3." (PMID 38071325, 2023). "We believe that using of PARPi monotherapy or in combination with radiation therapy is an appealing strategy for treating ARID1A-mutated cancers, as well as many other types of PI3K/Akt1-driven cancers." (PMID 36910637, 2023). "We screened for interactions with the ARID1A gene, implicated in both developmental disorders (OMIM: 135900) as well as cancer, suggesting growth control to be an important aspect of its function." (PMID 37028423, 2023). "ATR inhibitors, including Berzosertib and Ceralasertib, can potentially act on ARID1A-mutant cancer." (PMID 38203635, 2023). "Second, in our study, we use only the siRNA approach to decrease the expression of ARID1A in several cancer cell lines." (PMID 36910637, 2023). "AT‐rich interaction domain 1A, also known as BAF250a or SMARCF1, is a component of the SWI/SNF chromatin remodelling complex and is commonly mutated in many types of cancer." (PMID 38041544, 2023). "We showed that PI3K/Akt1 pathway plays an important role in the sensitization of cancer cell lines with compromised function of ARID1A to PARPi treatment." (PMID 36910637, 2023). "In conclusion, we successfully developed carcinoma by inducing the KO of Arid1a and Pten in the epithelium of endometriotic cysts, which were formed by the transplantation of small uterine pieces onto the peritoneum or ovarian surface." (PMID 37221199, 2023). "ARID1A-deficient cells are also sensitive to ATR inhibitors (ATRi), which have potential for cancer therapy in the near future." (PMID 36605718, 2022). "ARID1A, which encodes an important SWI/SNF component, was found to be frequently mutated in several types of cancer, and significantly contributes to tumorigenesis." (PMID 35531466, 2022). "Prior to examining the effects of ARID1A knockdown on carcinogenesis features and aggressiveness of cancer cells, the efficacy of siRNA specific to ARID1A (siARID1A) was first examined." (PMID 35069887, 2022). "In cases with somatic ARID1A and/or PIK3CA mutations, they were consistently found to be present across all cancer specimens, as well as any AE or TE from those cases." (PMID 35457244, 2022). "Recently, ARID1A, a paralog of ARID1B, whose deficiency is implicated in the promotion of cancer progression, was identified as being able to induce senescence and the progression of pancreatic intraepithelial neoplasia (PanIN)." (PMID 36361605, 2022). "One of the therapy paradigms examined in ARID1A mutant cancers is synthesised lethality, which relates to the lethal consequence of simultaneous alteration of two genes which, when separately disrupted, do not impact cell viability." (PMID 36212140, 2022). "Generally, mutated ARID1A, ARID1B and ARID2 were all related to the good prognosis of ICI therapy based on the pan-cancer population." (PMID 35239432, 2022). "Relatively few studies have been conducted investigating the importance of epigenetic modifications in the downregulation of ARID1A in cancer." (PMID 35611248, 2022). "The IC50 values of VE822 in both ARID1A expression groups of primary CRC cancers is close to the IC50 values of in the in vitro colony formation assay of ARID1A- and ARID1A+ cell lines." (PMID 36249060, 2022).
cancer (continued). "In human cancers, ARID1A drives cancer development and defines IFN responsiveness and immune evasion, resulting in poor immunotherapy responses." (PMID 36359251, 2022). "ARID1A also downregulates promoters of telomerase reverse transcriptase; thus, ARID1A silencing increases telomerase activity, adding to the survival of cancer cells." (PMID 36430148, 2022). "The mutational status in 409 cancer-associated genes of 10 Taiwanese patients with EAOC (8 EnOC; 2 ovarian CCC) showed that ARID1A was mutated in 50% of cases." (PMID 35457244, 2022). "Altogether, of 62,851 cancer patients with ≥1 cfDNA alteration in the blood, 3137 (5%) had ≥1 deleterious ARID1A alteration (a frequency similar to the ~6% generally reported in tissue sequencing), suggesting this non-invasive test’s value in detecting ARID1A." (PMID 36077815, 2022). "Herein, we explore, for the first time, the blood-derived cfDNA landscape of ARID1A alterations, a gene gaining increasing attention for therapeutic targeting in cancer, in a pan-cancer cohort." (PMID 36077815, 2022). "Since the cBAF complex requires either ARID1A or ARID1B, the inactivation of ARID1B has been viewed as a potential vulnerability for ARID1A-mutated cancers." (PMID 36605718, 2022). "Data from The Cancer Genome Atlas project (TCGA) revealed that ARID1A is significantly mutated in CRC, with the highest frequency of mutations (~39%) in cancers of the MSI type." (PMID 35611248, 2022). "It is also plausible that tissue has been analyzed for a wider array of rare cancers that have fewer ARID1A alterations and that that diluted overall tissue numbers." (PMID 36077815, 2022). "Therapeutic targets in cancer cells defective for the tumor suppressor ARID1A are fundamentals of synthetic lethal strategies." (PMID 36078038, 2022). "Mutations of the ARID1A gene are regarded as the main genetic disturbances present in CCOC and ENOC cancers." (PMID 36612107, 2022). "Through SWI/SNF complexes’ participation in the regulation of gene expression, ARID1A impacts many important cellular pathways and processes in healthy cells, and altered ARID1A plays a crucial role in the generation and propagation of the cancer state." (PMID 36077815, 2022). "We found that ECs harbored not only known mutations in driver genes, such as ARID1A, CTNNB1, PIK3CA, and PTEN, but also novel mutations in cancer-related genes, such as KMT2C and PRKAR1A." (PMID 35626111, 2022). "ARID1A, encoding a subunit of the SWI/SNF chromatin-remodeling complex, is the most frequently mutated epigenetic regulator in cancers." (PMID 36741696, 2022). "Suppression of ATR induces genomic instability and thus activation of programmed cell death in ARID1A- cancer cells." (PMID 36249060, 2022). "ARID1B, a paralog of ARID1A, has been recently recognized as a putative lethal target for ARID1A-mutant cancers, as ARID1B depletion impairs growth and destabilizes the SWI/SNF complex, which subsequently increases cell radiosensitivity." (PMID 36249060, 2022). "In this review, we summarize recent advances in understanding the biology of ARID1A in cancer development, with special emphasis on its roles in DNA damage repair." (PMID 36123603, 2022). "The present data show that combining ionizing radiation with ATR inhibitors is highly effective in eradicating ARID1A- CRC cancer cells." (PMID 36249060, 2022). "For example, ARID1A, a component of SWI/SNF chromatin-remodeling factor, is one of the most frequently mutated genes in various cancers." (PMID 36180906, 2022).
cancer (continued). "Subsequently, inactivating ARID1A mutations have been detected in a wide variety of human cancers, highlighting the epigenomic roles of ARID1A in cancer development." (PMID 36123603, 2022). "Expression reduction of ARID1A and its tumor suppressor activity have been extensively described in a broad spectrum of cancers, including CRC." (PMID 35611248, 2022). "Although ARID1A has a mutually exclusive homolog ARID1B, and both ARID1A and ARID1B are often co-mutated in human cancers, the creation of specific inhibitors is challenging due to the 60% homology between ARID domains." (PMID 36430148, 2022). "The ARID1A tumour suppressor protein is a component of the SWI/SNF chromatin remodelling complex, which is mutated in approximately 20% of all human cancers." (PMID 35647895, 2022). "ARID1A is the most frequently mutated SWI/SNF gene and one of ten most commonly mutated driver genes in human cancers." (PMID 35323214, 2022). "Recently, ARID1A was shown to be an essential regulator for the maintenance of GSH metabolism in cancer cells." (PMID 35531466, 2022). "The ubiquitinase Trim32 can ubiquitinate ARID1A and further promote its degradation, while USP11 inhibits the ubiquitination of ARID1A and maintains its cancer-inhibiting effect." (PMID 35715413, 2022). "A pan cancer study suggests that changes in ARID1A can be used as a biomarker for immunotherapy outcomes." (PMID 35028302, 2022). "AT-rich interaction domain 1A (ARID1A) encodes a protein that forms a subunit of the SWI/SNF chromatin-remodeling complex and its mutation has frequently occurred in multiple cancer types." (PMID 35884471, 2022). "ARID1A has been reported to be frequently mutated in a number of cancer types and PRKRIR has been reported as a cancer-associated somatic mutation gene in ESCC." (PMID 35615147, 2022). "Recent studies have revealed the feasibility of PARP inhibitors in treating patients with ARID1A-defective cancers." (PMID 36361605, 2022). "The encoded protein ARID1A, also known as BAF250a or SMARCF1, is the most frequently dysregulated SWI/SNF subunit in human cancer." (PMID 35125107, 2022). "Mutations in cancer-related genes (KMT2C, NOTCH2, PRKAR1A, SDHA, and USP6) and genes related to EC (ARID1A, CTNNB1, PIK3CA, and PTEN) were identified with high frequencies among the three samples." (PMID 35626111, 2022). "Considering that the mutation frequency of ARID1A is high in CRC, it is important to develop drugs for the selective targeting of ARID1A- cancer cells and integrate them with standard therapies to develop novel treatment options." (PMID 36249060, 2022). "ARID1A was shown to enhance cancer initiation in part due to its transcriptional limitation of Cyp2e1, which resulted in increased reactive oxygen species (ROS) production." (PMID 35028302, 2022). "ARID1a (BAF250), a component of human SWI/SNF chromatin remodeling complexes, is frequently mutated across numerous cancers, and its loss of function has been putatively linked to glucocorticoid resistance." (PMID 36344675, 2022). "Among them, ARID1A, TSC2, JAK3, CIC, CINNB1, and SETD2 were mutated at the early stage of carcinogenesis, which played an essential role in advancing early cancer development and progression." (PMID 35795211, 2022). "For instance, ARID1A depletion decreases the open histone mark (H3K27ac) at the enhancer region and transcriptionally activates a number of cancer related genes including PIK3IP1, SLC7A11, CDKN1A, TGF-β receptor, and SMAD3 among several others." (PMID 36123603, 2022). "(d) Others: PD-1/PD-L1 inhibitors have synthetic lethal effects in ARID1A- and PBRM1-deficient cancers." (PMID 36371186, 2022).
cancer (continued). "Although our data provide in silico information regarding the association between ARID1A mutations and PI3K/AKT pathway, its exact mechanism and function in human cancer cells has yet to be fully elucidated." (PMID 35070505, 2022). "Many of the 552 HERVH-dependent upregulated genes in ARID1A KO cells were enriched in cancer-related pathways." (PMID 35715442, 2022). "In ARID1A mutated cancers, the co-mutation of ARID1B destabilizes the SWI/SNF complex and damages cell proliferation, suggesting a potential target for malignancies harboring ARID1A mutations." (PMID 35303910, 2022). "ARID1B shares 60% sequence identity with ARID1A, also contains an ARID domain, and is also mutated (although at lower frequency) in a variety of cancers such as basal cell carcinoma, melanoma, and some gynecological cancers." (PMID 36605718, 2022). "Sub-cluster 15–4 is likely to be related to the function of monocyte CD300e and cancer ARID1A genes, which have recently attracted much attention." (PMID 34811710, 2022). "Another prospective therapeutic target in ARID1A mutant cancers is histone deacetylase (HDAC) activity." (PMID 34213777, 2021). "Second, these studies highlight the need to explore the vulnerabilities or synthetic lethality opportunities arising from these alterations, such as an increased dependency on BRD4 or the identification of ARID1B as a vulnerability in ARID1A-mutant cancers." (PMID 33284960, 2021). "We observed statistically significantly higher immune cell counts in tumors with ARID1A gene expression across various cancers." (PMID 34414106, 2021). "TP63 is a classical marker of squamous differentiation in cancer, and our studies suggest ATF3 induction is associated with TP63 expression in invading endometrial epithelial cells following ARID1A loss." (PMID 34941867, 2021). "The DNA binding subunit ARID1A, and the catalytic subunit SMARCA4 (BRG1) are the two most mutated BAF subunits across cancer types." (PMID 33826602, 2021). "Intriguingly, the distinct roles of the core subunit ATPase BRG1 and ARID1A in genome organization have been reported in two types of cancer cells." (PMID 34689165, 2021). "Multiple genes encoding subunits of the SWI/SNF complexes, including ARID1A, SMARCA4, PBRM1, and SMARCB1, are mutated in ~20% of all cancers." (PMID 33917230, 2021). "At late time points and in an ARID1A−/− line, molecular mechanisms of cancer are the most strongly engaged pathway." (PMID 34731603, 2021). "Nonetheless, a few act to propagate engagement with cancer pathways that become progressively enriched and ultimately dominate the phenotype of ARID1A−/− knockout cells." (PMID 34731603, 2021). "Current research focuses on associating the ARID1A mutation with other mutations in OCCC and using them as prognostic factors for malignant tumors." (PMID 34659566, 2021). "PIK3CA is one of the most frequently mutated genes along with ARID1A in OCCC, and co-mutation of Pik3ca and Arid1a in mouse ovaries causes cancer similar to human OCCC." (PMID 34172890, 2021).